MAVS (mitochondrial antiviral signaling protein)
Diseases named in the same sentence as MAVS in open-access papers (continued):
Sharing a sentence is not in itself a finding about the gene and the disease.
viral infection (continued). "Upon viral infection, Toll-like receptor 3 (TLR3) and RIG-I recruit their adaptor protein (TIR-domain-containing adapter-inducing interferon-β, TRIF for TLR3 and mitochondrial antiviral signaling protein, MAVS for RIG-I)." (PMID 30682859, 2019). "An indirect role of MAVS in NLRP3 inflammasome activation by viral dsRNA became apparent, thereby viral infection triggered MAVS-dependent plasma membrane permeabilization driving K+ efflux and NLRP3 activation." (PMID 31540165, 2019). "Nevertheless, even accidental activation of mitochondrial fission would presumably lead to a blockade of MAVS downstream signaling, resulting in reduced IFN synthesis and sustained viral infection." (PMID 29772718, 2018). "Here, using a single-step whole cell extract (WCE) preparation coupled to non-reducing SDS-PAGE and SDD-AGE analyses, we report the coexistence of MAVS oligomers and high MW aggregates upon constitutively active RIG-I ectopic expression and virus infection." (PMID 29385716, 2018). "In detail, following viral infection or stimulation by specific ligands, the caspase recruitment domain (CARD) of RIG-I and MDA5 becomes accessible for NLRC5 which competes with MAVS for binding, thus leading to dampened IRF3 activation." (PMID 30344524, 2018). "Through association with different partners, NLRX1 acts as a negative regulator to inhibit TLR, MAVS, and STING pathways, and as a positive regulator to facilitate autophagy in response to viral infection." (PMID 30559741, 2018). "Higher ROS levels increase MAVS downstream signaling resulting in elevated type I IFN synthesis and limited development of virus infection." (PMID 29772718, 2018). "IRF3 is recruited to MAVS polymers through phosphorylation of two conserved serine and threonine clusters in MAVS by IKKs or TBK1 upon virus infection." (PMID 29125880, 2017). "We also examined the time course binding of NLRX1 and MAVS and compared it with that of NLRX1 and FAF1 after the virus infection." (PMID 28542569, 2017). "In response to virus infection, RIG-I-like receptors (RLRs) sense virus RNA and induce MAVS to form prion-like aggregates to further propagate antiviral signalling." (PMID 28607490, 2017). "Following sensing of viral infection by RIG-I/MDA5 and activation of MAVS, TBK1 is activated which leads to the phosphorylation of the interferon regulatory factor 3 (IRF3)." (PMID 28883463, 2017). "In contrast, silencing MAVS largely abrogated the ability of PKR to induce IFN, as well as impairing responses to viral infection, such as VSV." (PMID 26939124, 2016). "In response to viral infection, RLRs form a complex with their essential adaptor, mitochondrial antiviral signalling protein (MAVS, also called IPS-1, VISA or Cardif) through homotypic caspase recruitment domain interaction." (PMID 27551434, 2016). "Upon viral infection, recognition of viral RNA by RIG-I induced a downstream signaling cascade, including MAVS, TBK1, IRF3." (PMID 27213432, 2016). "Upon sensing viral infection, particular PRR that contain caspase-recruiting domains (CARD), interacts with interferon-β promoter stimulator-1 (IPS-1, also known as VISA, MAVS or Cardif) through CARD–CARD interaction." (PMID 27449021, 2016). "The protection against viral infection in the TMEV 3D-Tg model, which is dependent on the presence of MDA-5 or MAVS signaling, supports this possibility." (PMID 27250711, 2016). "The results indicated that MAVS knockdown significantly inhibited MCCC1-induced IFN promoter induction, suggesting that the MCCC1-mediated upregulation of IFNs upon virus infection is MAVS-dependent." (PMID 27629939, 2016). "In response to virus infection, RIG-I senses viral RNA and activates the adaptor protein MAVS, which then forms prion-like filaments and stimulates a specific signalling pathway leading to type I interferon production to restrict virus proliferation." (PMID 26183716, 2015).
viral infection (continued). "MAVS was activated and was phosphorylated by IKB kinase complex after viral infection and thus NF-κB was activated by phosphorylated IKB." (PMID 25710018, 2015). "In this regard, the greater association of MAVS with c-FLIPL than with c-FLIPS during viral infection may profoundly affect not only the ability of RIG-I, FADD, and RIP1 to translocate to MAVS at the mitochondria, but c-FLIPL may also inhibit cleavage of MAVS by the CVB3 3Cpro protease." (PMID 24816846, 2014). "In conclusion, virus infection of airway epithelia induces, via a RIG-I/MAVS/IRF7 dependent pathway, both type I and III IFNs which drive two completely overlapping and redundant amplification loops to upregulate ISGs and protect from influenza infection." (PMID 24278020, 2013). "IFNβ-containing culture media were obtained from 293T cells transfected with a RIG-I signaling component (MAVS or TBK1) and TRIM11 or empty vector, and then used to treat Vero cells prior to viral infection with HSV-1 or VSV-GFP." (PMID 23675467, 2013). "Like WT MAVS, the QN2ED mutant formed high molecular weight aggregates after virus infection, suggesting that its inability to activate IRF3 is likely due to defective recruitment of TRAF proteins rather than a defect in polymerization." (PMID 23951545, 2013). "To confirm that loss of MAVS is responsible for increased cytokine production induced by γHV68, we “reconstituted” MAVS expression by lentivirus in Mavs−/− MEFs, and examined gene expression of cytokines (such as TNFα and CCL5) in response to viral infection." (PMID 22110409, 2011). "So far, the most definitive link connecting NF-κB activation to mitochondria is through MAVS, a MOM-resident protein that participates in the host innate immune response to viral infection." (PMID 18213395, 2008). "Upon viral infection, viral RNA is detected in the cytosol through intracellular MDA5/RIG-I-like receptors, which triggers the localization of the mitochondrial antiviral signaling (MAVS) protein to the mitochondrial outer membrane." (PMID 40960494, 2025). "Oxidative and endoplasmic reticulum stress significantly amplified type I IFN expression upon viral infection, but this effect was attenuated in cells expressing MAVS mutants lacking phosphorylation sites." (PMID 40837220, 2025). "As shown, TRIM22 enhanced the ubiquitination of MAVS following IAV-H1N1 or H3N2 infection, whereas TRIM22 knockdown reduced the ubiquitination levels of MAVS, underscoring the critical role of TRIM22 in viral infection." (PMID 40162781, 2025). "During viral infection, lactate can bind directly to the transmembrane domain of MAVS, inhibiting its polymerization and thereby facilitating the hijacking of RIG-I-MAVS by HK2-MAVS, which disrupts the normal glycolytic process and inhibits the downstream signaling of type I interferon." (PMID 39867891, 2024). "However, in the NLR family, there are members of great importance for inflammatory functions such as NLRP3 or NLRX1, which regulatory functions on RIG-I/MAVS pathway and are important in viral infection, and NOD2, a less studied effector in viral infections." (PMID 38668261, 2024). "In addition to virus infection, the iron metabolism-related gene HFE can also bind to MAVS for SQSTM1/p62-mediated MAVS degradation via selective autophagy." (PMID 38965634, 2024). "Whether and how palmitoylation of MAVS by ZDHHC7 directly regulates mitochondrial metabolism and function upon virus infection awaits further investigation." (PMID 39141356, 2024). "PRMT7 attenuates the binding of MAVS to TRIM31 and RIG-I by catalyzing the mono-methylation of MAVS at the R52 residue, but aggregated PRMT7 is incapacitated upon viral infection due to auto-methylation at the R32 residue, subsequently alleviating its suppressive effect on MAVS activation." (PMID 38970666, 2024).
viral infection (continued). "The activation of mitophagy leads to the degradation of mitochondrial antiviral signaling protein (MAVS), which upregulates the immune response and inflammation-related genes in response to viral infection by regulating the activation of NF-kappaB (NF-κB) and IRF3." (PMID 39516736, 2024). "In particular, viral infection induces the assembly of a RIG-I translocon consisting of RIG-I, TRIM25, and 14-3-3ε on MAMs to activate the RLR antiviral response by promoting RIG-I polyubiquitination and interaction with MAVS." (PMID 36980296, 2023). "Furthermore, immunofluorescence analysis showed that WDR77 colocalizes with MAVS in cells, and the interaction between WDR77 and MAVS was enhanced upon virus infection." (PMID 37563140, 2023). "In our experiments, we infected with VHSV 48 h post MAVS transfection, a timing geared towards allowing replication to occur in concert with the upregulation of IFN expression to avoid the complete suppression of virus infection or replication." (PMID 36851680, 2023). "Whereas, MAVS, RIG and related signals showed decreased expression after virus infection." (PMID 37711616, 2023). "Upon viral infection, IFIT3 expression is up-regulated, which limits the replication of RNA viruses (by direct inhibition of translation); however, IFIT3 has also an indirect antiviral effect through its interaction with MAVS." (PMID 37316325, 2023). "Furthermore, we examined the interaction between MAVS and WDR77 at different time points post virus infection." (PMID 37563140, 2023). "By contrast, NIX-dependent mitophagy acts as an intrinsic negative regulator of the RLRs-MAVS axis by preventing spontaneous aggregation of endogenous MAVS in the absence of viral infection." (PMID 37325622, 2023). "When MAVS was knocked down using siRNA, influenza virus infection was induced, and viral infection was not inhibited by CH treatment." (PMID 37711616, 2023). "Additionally, MAVS aggregation, IRF3 dimerization, and phosphorylation were enhanced in Wdr77CKO PEMs upon virus infection." (PMID 37563140, 2023). "For example, G2/I2 showed hyper-editing of type 1 interferon (IFN) receptors (IFNAR1 and IFNAR2), type 1 IFN-stimulated genes (ISGs) (e.g., EIF2AK2, DDX58/RIG-1, MAVS, TRIM56, and TRIM69) and genes involved in immune responses to viral infection (EIF2AK2, DDX58/RIG-1, MAVS, CASP8, CYCS, and HMGB1)." (PMID 35406793, 2022). "WNV infection of RIG-I and MDA5 double-knockout mice or MAVS knockout mice failed to induce innate immune response and scrubbed to the viral infection." (PMID 35061864, 2022). "Mechanistically, we demonstrated that TRIM18 recruited the protein phosphatase PPM1A to dephosphorylate TBK1, which inactivated TBK1 and blocked interactions of TBK1 with its upstream adaptors MAVS and STING, dampening type I IFN mediated antiviral signaling during virus infection." (PMID 35909127, 2022). "In the absence of viral infection, chemically induced oxidative stress can induce MAVS oligomerization and the activation of downstream signaling pathways." (PMID 35844503, 2022). "The mitochondrial antiviral-signaling protein (MAVS) is located in mitochondria or endoplasmic reticulum (ER) and considered as the receptor protein of RLR signaling pathway, by which IFN-β is effectively expressed at the early stage of virus infection." (PMID 35185855, 2022). "Our previous studies have shown that STAT1 can be activated through RIG-I/MAVS/Syk pathway at the early stage of viral infection, which is independent of cytokines and JAK signaling pathways." (PMID 36148221, 2022). "In addition, after viral infection, SIRT5 catalyzes MAVS desuccinylation at residue K7 to reduce the MAVS aggregates to limit MAVS activation and RLR signaling." (PMID 35795661, 2022).
viral infection (continued). "After viral infection, OTUD2 (also known as YOD1) interacts with MAVS through its UBX and Znf domains at the mitochondria, followed by the cleavage the K63-linked ubiquitin chains of MAVS that induced the abrogation of MAVS oligomerization to attenuate the IFN production." (PMID 35008917, 2022). "After virus infection, RIG-I and MDA5 sense the RNA and then translocate to the mitochondria, where they interact with the adaptor protein mitochondrial antiviral signaling (MAVS) to form a MAVS signalosome." (PMID 35874957, 2022). "Upon viral infection, EPRS may protect the mitochondrial antiviral signaling protein (MAVS) by blocking PCBP2-mediated ubiquitination." (PMID 36034844, 2022). "Mitochondrial antiviral signaling (MAVS) protein, also known as virus-induced-signaling adapter (VISA) or IFN-β promoter stimulator protein 1 (IPS-1), is located on the mitochondrial membrane and is critical to innate immune defense against viral infection." (PMID 34722508, 2021). "Considering RIG-I, MDA5, and mitochondrial antiviral signaling (MAVS) pathways to sense viral RNAs, our current study does not involve any viral infection model." (PMID 34291735, 2021). "Hence, the CARD domain of RIG-I binds to the CARD domain of the downstream adaptive molecule MAVS to induce its activation, and MAVS redistributes and accumulates on the mitochondrial surface to activate IRF3 in response to viral infection." (PMID 34917069, 2021). "In other words, the reduction in MAVS induced by aMPV/C infection did not occur at the transcriptional level at 48h after virus infection." (PMID 34696420, 2021). "Upon viral infection, decreased MMP might quickly thwart the MAVS complex’s structural rearrangement." (PMID 34360945, 2021). "Moreover, The TRIM family’s ubiquitination generally accompanies post-transcription regulation of MAVS (e.g., TRIM21, 25, 29, and 31) in response to virus infection." (PMID 34917069, 2021). "Similarly, MAVS and TBK1 induce the constitutive expression of IFN and ISGs, conferring on fish cells protection against virus infection." (PMID 33600488, 2021). "No obvious change occurred in MAVS expression in cells infected with UV-inactivated aMPV/C and in mock-infected cells during virus infection." (PMID 34696420, 2021). "As in vitro data show that MAVS is required to induce IFN production by activating NFKβ and IRF3, recent evidence also shows that mice lacking MAVS failed to induce IFN production in response to viral infection." (PMID 34841263, 2021). "Moreover, the expression of cyclophilin A is upregulated upon viral infection; cyclophilin A competes with TRIM25 for binding to MAVS." (PMID 34782737, 2021). "However, after viral infection, FAF1 is phosphorylated by activated IKKε, which promotes its depolymerization and lysosomal degradation and thus relieves MAVS inhibition." (PMID 32536927, 2020). "Consistently, the protein levels of MAVS are substantially increased in Rnf115−/− organs or cells without viral infection, and HSV-1-induced aggregation of MITA is impaired in Rnf115−/− cells compared to the wild-type counterparts." (PMID 33139700, 2020). "The related proteins revealed are MAVS (520 aa), ISG15 (a ubiquitin-like protein that has an essential role in the innate immune response to viral infection either via its conjugation to a target protein, ISGylation, or via its action as a free or unconjugated protein)." (PMID 33488570, 2020). "Finally, we provide data that highlight the molecular mechanism of RNF115-mediated dual roles in antiviral signaling by regulating homeostatic MAVS in uninfected cells and by promoting the activation of MITA after viral infection." (PMID 33139700, 2020). "In the context of viral infections, RIG-I induces MAVS-dependent inflammasome activation." (PMID 33488570, 2020).
viral infection (continued). "MAVS protein functions as an adaptor downstream of RIG-I or MDA5 to form signaling platforms that ultimately lead to IRF3 activation and type I IFN production in response to dsRNA sensing during viral infections." (PMID 32012730, 2020). "The expression of these innate immune factors, including RIG-I, MAVS and NLRP3, may be up-regulated by viral infections in simple hypertrophic tonsils." (PMID 32487224, 2020). "However, viral infection leads to geranylgeranylation and palmitoylation of Rac1, which inhibits the TRIM31–MAVS interaction and suppresses innate immunity; interestingly, under physiological conditions, Rac1 can also inhibit MAVS aggregation." (PMID 32536927, 2020). "Subsequent studies, however, failed to observe MAVS-dependency of NLRP3 activation by ATP or nigericin, restricting its role to viral infection-associated inflammasome activation." (PMID 31540165, 2019). "Interestingly, NLK exhibited a band similar to that of MAVS following viral infection, which implies that NLK is present in the prion-like complex together with MAVS after viral infection." (PMID 31324787, 2019). "Therefore, to study the effect of FTA on the RLRs signaling pathway during a viral infection, we measured the relative expression of RIG-I, MAVS, and NF-κB in the mouse lung tissues." (PMID 31757053, 2019). "A mitochondrial adaptor protein involved in innate immune responses to RNA viruses (see next section) mitochondrial antiviral-signaling protein (MAVS) mediated mitochondrial recruitment and activation of NLRP3 by canonical inflammasome stimuli, e.g. ATP and nigericin, or during viral infection." (PMID 31540165, 2019). "UBE2D2 is essential for the activation of MAVS and RIG-I in response to viral infection." (PMID 30405317, 2018). "Here, our results indicate that OTUD1 could utilize Smurf1 to downregulate MAVS/TRAF3/TRAF6 proteins and restrict IFNs production during viral infection." (PMID 29734366, 2018). "To further elucidate the novel mechanism, we sought to restoration of MAVS expression by overexpression of MAVS, miR-3470b inhibitor or siRNA-MAVS during viral infection, and markedly suppressed the effect of on BEFV replication was observed, whereas knockdown of MAVS had the opposite effect." (PMID 30587113, 2018). "We next sought to determine how viral infection affects the levels of OTUD1, Smurf1 and MAVS/TRAF3/TRAF6, and whether the regulation signaling of OTUD1-Smurf1-MAVS/TRAF3/TRAF6 occurs during viral infection." (PMID 29734366, 2018). "Consistent with our observation in the context of virus infections, we observed a specific interaction between simian MAVS and VP3 from simian RV RRV strain, and not with VP3 from murine and human RV strains." (PMID 30460894, 2018). "Previous study had showed that viral infection was able to up-regulate the expression of ISGs directly through MAVS signaling without activation of IFN receptor signaling." (PMID 29124042, 2017). "However, during virus infection, the mechanism which controls type I interferon (IFN) signaling via modulating the MAVS and NLRX1 interaction, needs to be investigated more in detail." (PMID 28542569, 2017). "Consistently, P5 fraction isolated from sh-Ube2N-treated MEFs showed no activity in stimulating IRF3 dimerization, suggesting that MAVS was not activated on virus infection." (PMID 28469175, 2017). "The interaction between NLRX1 and MAVS in non-infected cells was markedly reduced after viral infection in a time-dependent manner, importantly, there was a corresponding increase in FAF1-NLRX1 binding." (PMID 28542569, 2017). "However, after virus infection, FAF1 appears to displace MAVS from NLRX1 by competitive binding to NLRX1." (PMID 28542569, 2017). "Furthermore, NOD2 interacts with mitochondrial antiviral signaling protein (MAVS), which is essential for the production of IFN-β to suppress virus replication during viral infections." (PMID 29403486, 2017).